RNU1-55P (RNA, U1 small nuclear 55, pseudogene)
Gene: Small nuclear RNA gene on chromosome 20 (5,890,055 to 5,890,212, forward strand). Ensembl gene ENSG00000202380.
Homologues: Orthologues: chimpanzee U1 (99% identical), macaque U1 (94% identical), dog U1 (79% identical), guinea pig U1 (77% identical). Paralogues in human: RNU1-1 (87% identical), RNU1-2 (87% identical), RNU1-27P (87% identical), RNU1-28P (87% identical), RNU1-3 (87% identical), RNU1-4 (87% identical), RNVU1-18 (87% identical), RNVU1-29 (87% identical), U1 (87% identical), RNU1-148P (86% identical), RNU1-89P (86% identical), RNVU1-28 (86% identical), and 133 more.